TXN (thioredoxin)
Diseases named in the same sentence as TXN in open-access papers (continued):
Sharing a sentence is not in itself a finding about the gene and the disease.
leukemia (5 papers, 2011 to 2022). A malignant (clonal) hematologic disorder, involving hematopoietic stem cells and characterized by the presence of primitive or atypical myeloid or lymphoid cells in the bone marrow and the blood. "Thioredoxin (Trx) system regulates cellular ROS levels and helps maintain redox homeostasis of leukemia cells." (PMID 33292641, 2020). "It is composed of thioredoxin, thioredoxin reductase, and NADPH, and any of these elements have been reported to be altered in several tumors, including leukemia." (PMID 36139768, 2022). "Consistent with the present study, EANT enhanced the mRNA expressions of NFE2L2, CAT, TXN, HMOX1, and NQO1 genes in leukemia cells in response to EANT-induced oxidative stress." (PMID 34573042, 2021). "Altogether, our results show that the cellular antioxidant defense systems contribute to leukemia resistance to MTX, and targeting these pathways, especially the thioredoxin antioxidant system, may be a promising strategy for resensitizing ALL to MTX." (PMID 36531023, 2022). "Our study showed that the antioxidant systems of the cell are an important component of leukemia resistance to MTX, and targeting these pathways, especially the thioredoxin antioxidant system, may contribute to re-sensitize ALL to MTX." (PMID 36531023, 2022). "Altogether, our results indicate that the thioredoxin system exerts a compensatory effect over the GSH pathway that is not reciprocal and suggest that the thioredoxin system might be a potential target for MTX re-sensitization in leukemia cells." (PMID 36531023, 2022).
lung injury (5 papers, 2014 to 2025). "The imbalance of TXN homeostasis will lead to chemical nerve injury, while the TXN system can treat chemical nerve injury by targeting active substances." (PMID 39859536, 2025).
melanoma (5 papers, 2017 to 2024). A malignant, usually aggressive tumor composed of atypical, neoplastic melanocytes. "Both sarcoma and melanoma samples were highly positive for xCT, thioredoxin and v-ATPase in strong contrast with the adjacent normal tissues that were almost negative, confirming previous results." (PMID 28978047, 2017). "These targets could include thioredoxin secretion, heme oxygenase 1, and cell-surface expression of heat shock protein 70, previously shown to play a role in the immune response to melanomas." (PMID 35326683, 2022). "Although PRDX6, MAGOHB, NUCKS1, DCAF13, and TXN genes as a panel displayed weak prediction of ICB response, the panel robustly stratified overall survival in patients with melanoma treated with anti-PD1 following progression on anti-CTLA4 therapy." (PMID 37835514, 2023). "The expression of both TXN and TXNRD1 is known to be elevated in melanomas and other cancers." (PMID 35326683, 2022). "Inhibition of glutathione synthesis via the GCLC inhibitor buthionine sulfoximine has not been shown to be effective against melanomas in vitro or in vivo; however, in combination with cysteine transport or thioredoxin inhibition, greater efficacy is achieved." (PMID 35326683, 2022).
myocardial infarction (5 papers, 2020 to 2025). Gross necrosis of the myocardium, as a result of interruption of the blood supply to the area, as in coronary thrombosis. "For example, thioredoxin has been found to sustain mitochondrial morphology and thus attenuate myocardial infarction through redox-dependent activation of CREB signaling." (PMID 34211623, 2021). "Tr1 plays a role in restoring oxidized proteins via thioredoxin, which alleviates the effects of myocardial infarction." (PMID 33081396, 2020). "Medali and coworkers used left anterior descending coronary artery permanent ligation to create myocardial infarction in mice to test the effects of thioredoxin-1 (Trx-1), Trx-80, and mimetic peptide of Trx-1 (Ac-Cys-Pro-Cys-amide, CB3) on cardiomyocyte apoptosis and cardiac function." (PMID 40650199, 2025).
schistosomiasis (5 papers, 2008 to 2023). An infectious disease caused by parasitic trematodes of the genus Schistosoma that colonize human blood vessels and release eggs that can cause granulomatous reactions leading to acute (swimmer's itch or acute schistosomiasis syndrome) or chronic disease. "Thioredoxin/glutathione reductase (TGR) from the platyhelminthic parasitic worms has recently been identified as a drug target for the treatment of schistosomiasis." (PMID 37780207, 2023). "Two principal components of this defense system have been recently identified in S. mansoni as thioredoxin/glutathione reductase (TGR) and peroxiredoxin (Prx) and as such these enzymes present attractive new targets for anti-schistosomiasis drug development." (PMID 18235848, 2008). "Two principal components of this defense system, thioredoxin/glutathione reductase (TGR) and peroxiredoxin (Prx2), have been recently identified and validated as targets for anti-schistosomiasis drug development." (PMID 18235848, 2008).
type 2 diabetes (5 papers, 2007 to 2025). "We previously reported sequence analyses of other candidate genes for type 2 diabetes on Chr 11 including glucose transporter 4, thioredoxin, and nucleoredoxin." (PMID 32703163, 2020).
cardiac hypertrophy (4 papers, 2013 to 2023). "Another study showed the role of TXNIP as a therapeutic target for the treatment of myocardial hypertrophy by attenuating oxidative stress caused by TXNIP activation through its binding and TXN release." (PMID 37368371, 2023). "It has been demonstrated that myocardial hypertrophy contributes to TrxR1 expression and/or heart failure; it has been proven that the more pronounced is the heart failure, the higher is the thioredoxin level." (PMID 31362438, 2019). "In cardiac tissue, thioredoxin regulates pressure-overload-induced cardiac hypertrophy." (PMID 24141185, 2013). "Compared with wild-type animals, those without thioredoxin had greater cardiac hypertrophy, while overexpression of the protein resulted in attenuated cardiac size." (PMID 24141185, 2013).
head and neck cancer (4 papers, 2009 to 2021). A primary or metastatic malignant neoplasm affecting the head and neck. "The hypothesis that the Akt inhibitor, perifosine (PER), combined with inhibitors of glutathione (GSH) and thioredoxin (Trx) metabolism will induce cytotoxicity via metabolic oxidative stress in human head and neck cancer (HNSCC) cells was tested." (PMID 19746172, 2009).
heart failure (4 papers, 2019 to 2025). Inability of the heart to pump blood at an adequate rate to meet tissue metabolic requirements. "The causal role of oxidative stress in heart failure is also supported by gene transfer studies of the three primary antioxidant enzymes (SODs, catalase, and glutathione peroxidase), of thioredoxin, and of heme oxygenase-1." (PMID 34829874, 2021). "The causal role of oxidative stress in heart failure is highlighted by gene transfer studies of three primary antioxidant enzymes, thioredoxin, and heme oxygenase-1, and is further supported by gene therapy studies directed at correcting oxidative stress linked to metabolic risk factors." (PMID 34829874, 2021). "Since IDH2 also produces NADPH for GSH/GSSG and the thioredoxin system to maintain redox homeostasis within the mitochondria, impaired IDH2 activity therefore was suggested as an early mitochondrial oxidative stress marker in heart failure." (PMID 39594567, 2024).
ischemic stroke (4 papers, 2019 to 2025). A stroke disorder caused by obstruction of blood flow to the brain, due to thrombotic (local blood clot formation) or embolic (due to a blood clot or other material traveling from another site) event. "Keywords such as ischemic stroke, biomarkers, neurofilament light chain (NfL), bilirubin, thioredoxin, netrin-1, omentin-1, circular RNA, diffusion tensor imaging, EEG, TMS, motor recovery, and machine learning." (PMID 41303115, 2025). "In addition, polydatin upregulated the endogenous antioxidant nuclear factor erythroid 2-related factor 2, heme oxygenase-1, the thioredoxin pathway, and eventually reversed ischemic-stroke-induced elevation of ROS and inflammation in ischemic cortical tissue." (PMID 31293416, 2019).
liver cancer (4 papers, 2015 to 2023). An epithelial or non-epithelial malignant neoplasm that arises from the liver. "The amounts of three key proteins in the TXN system, TXNRD1, TXN, and peroxiredoxin 1 (PRDX1), in tumor and surrounding normal tissue samples from the three lung and three liver cancer patients were examined in duplicate by western blotting." (PMID 26569310, 2015).
multiple myeloma (4 papers, 2015 to 2025). "Increased thioredoxin level has been reported to be associated with carcinogenesis; however, the role of thioredoxin in bortezomib drug resistance of myeloma remains unclear." (PMID 29482577, 2018). "Subsequent prioritization revealed thioredoxin (TXN) as a candidate showing significant differential expression between multiple myeloma (MM) patients and controls, with elevated TXN levels observed in MM specimens." (PMID 40092696, 2025). "Previous studies have also found TXN to be overexpressed in primary myeloma cells isolated from bortezomib-resistant MM patients, and that overexpression of TXN correlated with poor overall survival in patients with MM." (PMID 33668794, 2021). "In bortezomib-resistant myeloma cell lines, TXN inhibition overcomes adaptive bortezomib resistance." (PMID 33668794, 2021). "Thioredoxin provides a potential target for clinical therapeutics against multiple myeloma, particularly for bortezomib-resistant/refractory myeloma patients." (PMID 29482577, 2018). "In summary, we showed that upregulation of thioredoxin expression correlated with the development of bortezomib drug resistance in multiple myeloma." (PMID 29482577, 2018). "Thioredoxin expression was significantly upregulated in bortezomib-resistant myeloma cells and the change correlated with the increase of bortezomib concentration." (PMID 29482577, 2018). "Our studies provide molecular rationale and justification for targeting thioredoxin in the treatment of bortezomib relapsed/refractory myeloma." (PMID 29482577, 2018). "We tested the effects of thioredoxin inhibitor on the survival and drug resistance in bortezomib-resistant myeloma cells in vivo and in vitro." (PMID 29482577, 2018). "Thioredoxin inhibitor (PX12) was used to determine the effectiveness of thioredoxin inhibition in the treatment of bortezomib-resistant myeloma cells." (PMID 29482577, 2018). "Altogether, these findings demonstrated the clinical significance for TXN in myeloma, especially in bortezomib-resistant multiple myeloma." (PMID 29482577, 2018). "Inhibition of thioredoxin by shRNA or thioredoxin inhibitor re-sensitized bortezomib-resistant myeloma cells to bortezomib treatment." (PMID 29482577, 2018). "Thioredoxin gene knockdown using specific shRNA sensitized bortezomib-resistant myeloma cells to bortezomib efficiency in vitro and in vivo." (PMID 29482577, 2018). "Compared to their parental BTZ-sensitive cells, BTZ-resistant myeloma cells demonstrated a significant upregulation of both thioredoxin mRNA gene expression and protein expression." (PMID 29482577, 2018). "Using chemical activator of mTOR and ERK, we demonstrated an important role of mTOR and ERK in the anti-myeloma effects induced by thioredoxin inhibition." (PMID 29482577, 2018). "Mechanistically, we have demonstrated that inhibition of thioredoxin re-sensitize bortezomib-resistant myeloma cells through the activation of mitophagy." (PMID 29482577, 2018). "Taken together, our findings demonstrate the potential of targeting thioredoxin to re-sensitize BTZ-resistant multiple myeloma to bortezomib treatment." (PMID 29482577, 2018). "The role of thioredoxin in the survival of bortezomib-resistant myeloma cells was determined by specific shRNA knockdown in vitro and in vivo." (PMID 29482577, 2018). "Compared to myeloma patients with low TXN expression, patients with higher TXN expression was associated with a shorter overall survival." (PMID 29482577, 2018). "Our findings demonstrated that increased thioredoxin plays a critical role in bortezomib resistance in multiple myeloma through mitophagy inactivation and increased mTOR and ERK1/2 phosphorylation." (PMID 29482577, 2018). "We further showed that the combination of bortezomib and thioredoxin inhibitor suppressed the growth of bortezomib-resistant myeloma cells through mitophagy activation." (PMID 29482577, 2018).
multiple myeloma (continued). "Additionally, we aimed at investigating the effects of thioredoxin on mitophagy in bortezomib-resistant myeloma cells." (PMID 29482577, 2018). "Taken together, our results supported our hypothesis that thioredoxin inhibition enhances bortezomib sensitivity in BTZ-resistant myeloma cells via mitophagy activation." (PMID 29482577, 2018). "We indeed showed that inhibition of thioredoxin by shRNA knockdown or pharmacological approach with PX12 could re-sensitize the bortezomib-resistant myeloma cells to bortezomib in vitro and in vivo in myeloma xenograft mouse models." (PMID 29482577, 2018). "Finally, thioredoxin was overexpressed in primary myeloma cells isolated from bortezomib-resistant myeloma patients and overexpression of thioredoxin correlated with poor overall survival in patients with multiple myeloma." (PMID 29482577, 2018). "We hypothesized that thioredoxin plays an important role in bortezomib drug resistance in multiple myeloma, providing a novel therapeutic target against cancer drug resistance in the treatment of multiple myeloma." (PMID 29482577, 2018). "When compared to the CD138− cells, TNX mRNA was significantly increased in the CD138+ plasma cells, suggesting that TXN is upregulated in myeloma cells in comparison to non-myelomatous cells of the same patient." (PMID 29482577, 2018). "We have also analyzed and compared the expression of thioredoxin in CD138+ myeloma cells from newly diagnosed myeloma patients, myeloma patients that were treated with bortezomib containing regimen, and relapsed/refractory myeloma patients who had prior exposure to bortezomib." (PMID 29482577, 2018).
neuroblastoma (4 papers, 2014 to 2021). Neuroblastoma (NB) is the most common solid, extracranial childhood tumor. "Treatment of SH-SY5Y human neuroblastoma cells with different concentrations of H2O2 led to decreased mRNA expression of TXN, which was exacerbated by induced mitochondrial dysfunction." (PMID 34208977, 2021). "Extracellular activation of the thioredoxin redox system, up-regulated in malignant tumours, has been shown to inhibit TIMP but not MMP activity in vitro and in models of human neuroblastoma and UV irradiated dermal fibroblasts." (PMID 24473089, 2014).
Parkinson disease (4 papers, 2016 to 2025). A progressive degenerative disorder of the central nervous system characterized by loss of dopamine producing neurons in the substantia nigra and the presence of Lewy bodies in the substantia nigra and locus coeruleus. "Dhd is the fly homolog of human TXN and has been shown to alleviate dopaminergic neuron loss induced in a fly model for Parkinson's disease." (PMID 27197210, 2016). "Research indicates that elevated TXN expression in conditions such as Parkinson’s disease and cancer impedes the progression of ferroptosis." (PMID 40299574, 2025). "ASK-1 is complexed by Thioredoxin, and this binding prevents apoptosis, as reported in an in vitro model of Parkinson’s disease, where Thioredoxin shows inhibition of the proapoptotic protein ASK-1, and where compounds that enhance this binding act as cell protectors." (PMID 34571838, 2021).
skin inflammation (4 papers, 2016 to 2025). "Mala S 13 is a homolog of human thioredoxin, and the CD4+ T cells cross react with human thioredoxin, leading to AD skin inflammation." (PMID 33575223, 2020). "TXN, a redox-active protein induced by diverse cellular stresses, has demonstrated therapeutic efficacy in various inflammatory disease models, including viral pneumonia, acute lung injury, gastric injury, dermatitis, and others." (PMID 41463387, 2025). "Geranylgeranylacetone (GGA) exerts cytoprotective activity against various toxic stressors via the thioredoxin (TRX) redox system; however, its effect on skin inflammation and molecular mechanism on inducing the TRX of GGA is still unknown." (PMID 37760004, 2023).
Stroke (4 papers, 2017 to 2025). Sudden impairment of blood flow to a part of the brain due to occlusion or rupture of an artery to the brain. "At the same time, there have been links reported between stroke outcomes and metabolic regulators like omentin-1, neurotrophic and angiogenic modulators like netrin-1, and oxidative stress markers like thioredoxin." (PMID 41303115, 2025). "Thioredoxin (Trx), also one of the body's antioxidant enzymes, has been found to improve outcomes after stroke." (PMID 36438975, 2022). "Antioxidant agents driving the upregulation of HO-1, such as dimethyl fumarate, gastrodin, and thioredoxin, have been reported beneficial in models of stroke and also reduce microglial activation and stroke-related neuroinflammation." (PMID 29202856, 2017). "Combining vascular and trophic biomarkers (netrin-1, omentin-1, and circRNAs) with injury markers (NfL) and oxidative stress indicators (thioredoxin and bilirubin) moves stroke assessment beyond lesion quantification to evaluating repair capacity and systemic resilience." (PMID 41303115, 2025). "NRF2 target genes include several antioxidant enzymes including PRDX1, thioredoxin 1 (TXN1), and heme oxygenase 1 (HMOX1) and its activation affords protection in animal models of stroke." (PMID 32733466, 2020).
acute kidney injury (3 papers, 2015 to 2024). Sudden and sustained deterioration of the kidney function characterized by decreased glomerular filtration rate, increased serum creatinine or oliguria. "Furthermore, recombinant long-acting TXN has been shown to ameliorate the transition from acute kidney injury to chronic kidney disease by modulating renal oxidative stress and inflammation." (PMID 38846934, 2024).
allergic asthma (3 papers, 2010 to 2024). A asthma with a basis in a pathological type I hypersensitivity reaction. "Thioredoxin, a reducing protein, may also inhibit experimental allergic asthma and airway remodeling." (PMID 20925946, 2010).
Allergy (3 papers, 2012 to 2024). An allergy is an immune response or reaction to substances that are usually not harmful. "An overexpression of thioredoxin in the wheat endosperm was found to increase the solubility and decrease the allergenicity of gliadins in a canine allergy model, indicating that the high expression in seeds by gene recombination reduces their allergenicity." (PMID 36900471, 2023). "A cDNA library from whole adult P. interpunctella was screened with the serum of a patient with indoor allergy and IgE to moths, and thioredoxin was identified as an IgE-binding protein." (PMID 22844539, 2012).
diabetic nephropathy (3 papers, 2014 to 2025). "Tranilast reduces ROS generated from zymogen-stimulated polymorphonuclear leukocytes, and also decreases oxidative stress in diabetic nephropathy by modulating thioredoxin." (PMID 24751945, 2014).
Hepatic fibrosis (3 papers, 2015 to 2021). The presence of excessive fibrous connective tissue in the liver. "These were proteins known to be involved in dendritic cell maturation, NRF2 oxidative stress response, hepatic fibrosis and the thioredoxin pathway." (PMID 28659381, 2017). "Importantly, it was previously reported that serum levels of thioredoxin, which is a stress-induced protein, increase relative to the degree of hepatic fibrosis, and that high serum concentrations of thioredoxin may indicate advanced hepatic fibrosis." (PMID 25871387, 2015). "Also, β-carotene, from other algae D. Saline, exerted its antioxidant through inducing catalase and thioredoxin enzymes that attenuated STZ-induced diabetic neuropathy and elevated the levels of GSH with a decrease in MDA opposing hepatic fibrosis induced by TAA in rats." (PMID 33628797, 2021).